CXCL10 (C-X-C motif chemokine ligand 10)
Diseases named in the same sentence as CXCL10 in open-access papers (continued):
Sharing a sentence is not in itself a finding about the gene and the disease.
cancer (continued). "CXCR3 is highly expressed in metastatic cancer cells, and its binding with chemokine ligands, such as CXCL10, enhances the migration and invasive motility of cells." (PMID 38275412, 2024). "In contrast, the biomarkers uPA, IL-18R1, EN-RAGE, CASP-8, MCP-2, TNFβ, CD5 and CXCL10, whose functions are related to cancer or inflammatory processes, had their expression inhibited." (PMID 39247198, 2024). "Carcinogen exposure promotes inflammatory cytokine secretion, including CCL5 and CXCL10, by cancer cells." (PMID 37843274, 2023). "The self-dsRNA initiates type I interferon response consisting of IFNα, IFNβ, and CXCL10 by binding TLR3 on cancer cells in a paracrine manner." (PMID 36979348, 2023). "Meanwhile, the interleukin 6 (IL6), CXC chemokine Ligand-5 (CXCL5), and CXC chemokine Ligand-10 (CXCL10) expressions were inhibited, and the cancer-promoting effect was reversed by COL12A1 knockdown." (PMID 36900272, 2023). "Our data demonstrates high accuracy using a multi-marker panel incorporating the CXCL10 “active ratio” as a method to discriminate benign from malignant disease." (PMID 37958440, 2023). "In this study we report the use of a multi-marker panel, including the measurement of IL6 and the CXCL10 active ratio, for identification and differentiation of benign from malignant tumors." (PMID 37958440, 2023). "As we found after stimulation of cancer cells with IFNγ/Pam3SCK4, cancer cells begin to secrete CXCL10." (PMID 37445941, 2023). "CXCL10 is produced early in cancer progression and can be modified through enzymatic cleavage to produce an inactivated protein." (PMID 37958440, 2023). "Interferon-γ-inducible protein 10 (IP-10), also known as Chemokine C-X-C ligand 10 (CXCL10), is predominantly secreted by monocytes, endothelial cells, fibroblasts, and cancer cells." (PMID 37907991, 2023). "Circulating CXCL10 can stimulate cancer cell recruitment to bone and the formation of osteolytic bone metastasis." (PMID 37509653, 2023). "M1 macrophages produce angiostatic substances which regulate the development of immunity response against cancer and CXCL10 has been identified as a marker of M1 macrophages." (PMID 37540227, 2023). "The cytokines C-C motif chemokine ligand 5 (CCL5) and C-X-C motif chemokine ligand 10 (CXCL10) can induce migration of intratumoral CD8+ T cells in cancer." (PMID 37767098, 2023). "The levels of cytokines such as IL1a, IFNB1, CD80, CD86, and CXCL10, which are important for inducing an immune response by macrophages within cancer tissue, were upregulated in PBMCs in a RIG-I-dependent manner." (PMID 37543704, 2023). "At the gene-level, the cytolytic granzyme A (GZMA) and K (GZMK) enzyme, CD8A and the chemokine CXCL10 illustrious of T and NK-cells and the testis antigen SPAG5 were associated with infiltration to cancer tissue." (PMID 37391505, 2023). "The c-Score, derived from expression of CCL4, CCL5, CXCL9, and CXCL10, identified subpopulations of tumors across cancer types with hallmarks of T cell-inflammation." (PMID 37558751, 2023). "Docetaxel induced a secretion of many factors including CXCL10, suPAR, and uPA from cancer cell lines, while WBCs remained unresponsive." (PMID 37957750, 2023). "A study using an in vitro co-cultured system demonstrated that nab-PTX inhibited CAF-induced cancer cell migration, invasion, and EMT phenotype by increasing the expression of CXCL10 in cancer cells to counteract the effect of IL-6 secreted by CAFs." (PMID 35327514, 2022). "CRISPR Cas9 invalidation of TLR9 impedes CXCL10 production by cancer cells, T cells recruitment and antitumor effect of chemoimmunotherapy plus MEK inhibitor." (PMID 35529902, 2022). "Mechanistically, BAY1082439 converts cancer cell-intrinsic immune-suppression to immune-stimulation by promoting IFNα/IFNγ pathway activation, β2-microglubin expression and CXCL10/CCL5 secretion." (PMID 35013322, 2022).
cancer (continued). "The receptor for CXCL10, CXCR3, has a pleiotropic role across cancer models and has been variously associated with recruitment of effector and suppressive/regulatory T cell populations." (PMID 35844527, 2022). "Because of the multifaceted effect of CXCL10 on the biological behavior of various cancers, it is challenging to utilize CXCL10 as a therapy target." (PMID 35755810, 2022). "Our previous study showed that IL25 was not directly affecting the growth, apoptosis, or migration in HCC, but promoted macrophages secret CXCL10 and led to cancer metastasis." (PMID 35359953, 2022). "This can be explained by different reagents, expression of CXCL10 in different cancers and the exclusion criteria of the healthy controls in different studies." (PMID 36207693, 2022). "This suggests that the upregulation of CXCL9, CXCL10 and CXCL11 is a common event in the cancers with viral or bacterial association." (PMID 35433690, 2022). "In GEO database, we validated that CXCL10 was highly expressed in cancer cases and negatively correlated with the prognosis of PAAD." (PMID 35083488, 2022). "Although TFR1-positive cancer cells can be killed by H-ferritin drug nanocarrier when treated with IFN-γ, TFR1-deficient cells can upregulate the expression of PD-L1, CXCL9, and CXCL10 to promote immune escape." (PMID 36082181, 2022). "We were shocked to learn that all three immunologic activation genes (CXCL10, RXRG, and SCG2) have been linked to cancer progression." (PMID 36685954, 2022). "Both CXCL9 and CXCL10 are chemokines secreted by monocytes, endothelial cells, fibroblasts and cancer cells in response to stimulation by IFN-γ." (PMID 36605208, 2022). "Using a drug screening, we observed that drug-inhibiting MAPK pathway enhances CXCL10 production by cancer cells treated by chemotherapy." (PMID 35529902, 2022). "CRISPR Cas9 invalidation of Optn or Atg5 gene in cancer cells impedes the capacity of the treatment to trigger CXCL10 production by cancer, the recruitment of CD8 T cells and the therapeutic effect of the association." (PMID 35529902, 2022). "Of note, several cancer associated genes such as CDH6, FOXM1, NAAA and CXCL10 were amplified and upregulated." (PMID 36352274, 2022). "These pro-inflammatory cytokines, such as IFN-γ and tumor necrosis factor (TNF), and chemokines, such as CXCL10, are critical for modulating adaptive immune response to inhibit cancer cells in the TME." (PMID 35455671, 2022). "The differences between CXCL9 and CXCL10 in their biological functions, possibly through biased signaling, and their possible relevance to cancer immunotherapy have been discussed." (PMID 36479091, 2022). "Levels of circulating CXCL10 are known to increase with age, in some forms of cancer and in some autoimmune diseases." (PMID 36164329, 2022). "It is well established that the IFN-γ signaling pathway regulates CXCL9 and CXCL10 expression in cancer cells." (PMID 36284313, 2022). "Cxcl10 is a chemokine produced by cancer cells that can activate mast cells and promote their recruitment to solid tumors." (PMID 35565345, 2022). "Immunostimulatory danger-associated molecular patterns (DAMPs) (such as ANXA1, CALR, and HMGB1) and cytokines (such as IFN and CXCL10) were used to evaluate the immunogenicity of cancer cell death." (PMID 36003383, 2022). "While HLA-I+ cancer cells released key effector cytokines and chemokines, such as CXCL10, CCL4, CCL5, and IFN-γ, HLA-I–deficient cancer cells had a limited release of proinflammatory cytokines." (PMID 35503263, 2022). "CXCL11 and CXCL10 are secreted mainly by monocytes, endothelial cells, fibroblasts, and cancer cells in response to IFN-γ and are synergistically enhanced by IFN-α." (PMID 35432485, 2022).
cancer (continued). "What's more, the higher the expression of CXCL10 in cancer cells, the stronger the cancer cells’ sensitivity to LDK-378, brigatinib, alectinib, and PF-06463922." (PMID 36091778, 2022). "To start, first different expression patterns of TMPRSS2 and CXCL10 in multidisciplinary cancer types were analyzed using the TIMER database." (PMID 36239108, 2022). "Anthracyclines can activate the IFN response in the stressed/dying cancer cells, leading to the production and secretion of Type I interferons and CXCL10." (PMID 36139473, 2022). "Specifically, we found that DAAM2 was positively correlated with the expression of critical immunomodulators, such as CCL5, CXCL9, and CXCL10, as well as the activities of the cancer-immunity cycle." (PMID 35281277, 2022). "In multiple cancer models, it has been shown that CXCL10 induces cancer cell proliferation and upregulates invasion-related properties." (PMID 34944879, 2021). "Here, we observed significant upregulation in CXCL10 expression in all cancer stages for both LUAD and LUSC patients." (PMID 33585826, 2021). "Specifically, we discovered that IFITM3 was positively correlated with the expression of critical immunomodulators, such as CCL5, CXCL9, and CXCL10, as well as the activities of the cancer-immunity cycle." (PMID 34456915, 2021). "Alternatively, cancer cells with activated β-catenin signals suppress the accumulation of cDC1 in cancer cells, resulting in decreased production of CXCL10." (PMID 34071550, 2021). "The chemokines CXCL9 and CXCL10, secreted upon exposure to zymosan or yeast-b and zymosan, respectively, are produced by monocytes, macrophages and cancer cells in response to IFN-y." (PMID 32860527, 2021). "In some types of cancers, MSCs enhance tumor growth by producing CXCL10, a chemokine that interacts with CXCR3 expressed on CSCs." (PMID 35096289, 2021). "Regarding animal preclinical studies, as CXCL9 and CXCL10 mostly affect anti-cancer immunity the immunocompetent models are favorable." (PMID 34944943, 2021). "Our collaborative study with Israel Vlodavsky and his team was among the first studies showing that systemic administration of CXCL10-Ig restrains cancer diseases." (PMID 34944943, 2021). "For example, the median cluster has lower expression of CXCL9 and CXCL10, which have been shown to be associated with TIL infiltration in human cancers and draw dendritic cells (DC) and CD8+ T cells 39-41." (PMID 33403028, 2021). "The production of CXCL10 by cancer cells acts as a chemoattractant for anti-tumorigenic immune cell subsets such as effector T cells." (PMID 34001994, 2021). "Firstly, we analyzed the different expression patterns of ACE2 and CXCL10 in multidisciplinary cancer types using the TIMER database." (PMID 33585826, 2021). "A significant fraction of these cancers contained CD163+pSTAT1Y701+ M1-type Mφ producing CXCL10 and surrounded by CD3 T-cell infiltration." (PMID 34220848, 2021). "CXCL10 was the highest overexpressed cytokine that showed an upregulation of almost 200 times upon treating the cancer cells with Rintatolimod." (PMID 34207861, 2021). "The TLR3 agonist Poly(I:C) induced the expression of the IRF3 target genes IFNB and CXCL10 in all tested cancer cell lines suggesting that defects upstream of TBK1/IKKe render the cancer cells unresponsive to STING agonists." (PMID 33790360, 2021). "CCL5, CXCL9, CXCL13, CXCL10, and CXCL11 were also among the top chemokine genes associated with the gene expression-based immune scores across multiple cancer types." (PMID 34030676, 2021). "Doxorubicin and PDT-treated cancer cells also upregulate a type I interferon (IFN-1) signaling cascade resulting in C-X-C motif chemokine ligand 10 (CXCL10) secretion and finally in DC maturation." (PMID 34073766, 2021). "Data analysis of scRNAseq pan-cancer dataset confirmed the existence of a CXCL10+IRF1+ STAT1+ M1-type Mφ across human cancers displaying activation of antigen presenting and cross presentation gene programs." (PMID 34220848, 2021).
cancer (continued). "After that, we generated an interactive heat map by using GEPIA 2 which compared the expression level of ACE2 and CXCL10 along with both cancer types, LUAD, and LUSC." (PMID 33585826, 2021). "Among them, CXCL10 and 16 were significantly increased in mononuclear/macrophage cells of the three cancers." (PMID 34439306, 2021). "The classic view on CXCL10 is that it prevents cancer through paracrine signaling as CXCL10 plays an important role in the recruitment and activation of immune cells." (PMID 34504204, 2021). "Among the four different cancer stages, the topmost elevated expression of CXCL10 was found in stage 2 for LUAD patients and stage 4 of LUSC patients." (PMID 33585826, 2021). "CXCL10 is up-regulated in many cancer types including RCC, where very high levels compared with healthy individuals have been reported." (PMID 34200459, 2021). "The expression levels of six chemokine genes (CCL5, CXCL9, CXCL13, CXCL10, CXCL11, and CCL19) were significantly associated with the image-based immune scores across all 13 tested cancer types." (PMID 34030676, 2021). "While CXCL11-Ig based therapy inhibited inflammatory autoimmunity within the central nervous system, administration of CXCL10-Ig suppressed cancer." (PMID 34944943, 2021). "CXCL10 and other chemoattractant cytokines are transcriptional targets of the IFNγ pathway and their expression in cancer often correlates with clinical response to immune checkpoint blockade." (PMID 33446805, 2021). "It is generally accepted that CXCL10 enhances anti-cancer immunity, and by so doing limits cancer development." (PMID 32547545, 2020). "CXCL10 is a member of interferon-inducible proteins, which is increasingly being considered as a pro-tumorigenic factor in various cancers, including CRC." (PMID 33198757, 2020). "It is possible that CXCL10 and perhaps pro-cancer function is due to its chemotactic properties for cancer cells." (PMID 32547545, 2020). "Since CXCL10 is a chemokine important for recruiting immune cells, its increased production would sensitize cancer cells to ICIs treatment." (PMID 33214545, 2020). "CXCL10 is known as one of the key immunomodulators in cancer and its high expression upon combined INFG and TNFA stimulation has been demonstrated in primary thyrocyte cell cultures." (PMID 32603365, 2020). "Particularly, previous studies have shown that CXCR3/CXCL10 signaling promotes metastasis in several cancer types." (PMID 33195424, 2020). "It was previously demonstrated that CXCL10, CXCL13 and other chemokines are closely associated with the occurrence and development of cancer." (PMID 32236620, 2020). "CXCR3 recognizes CXCL9 (Mig) and CXCL10 (IP10) which is presented on the inner lining of cancer vasculature." (PMID 33262763, 2020). "CXCL10 expression was almost exclusively detected in cancer cells, based on histological analysis performed by a trained liver pathologist (AQ)." (PMID 33234602, 2020). "Of the three CXCR3 ligands most of the attention has been drawn thus far to CXCL10, as a candidate for cancer immunotherapy." (PMID 32547545, 2020). "A recent study showed that overexpression of CXCL5, CXCL9, and CXCL10 improved the immune function of cancer patients." (PMID 33323542, 2020). "One is that the discrepancy between the studies is because the role of CXCL10 / CXCL9 varies between different cancer disease." (PMID 32547545, 2020). "Increased expression of CCR5 and CXCL10, which were upregulated in the cancer group, predicted a significantly shorter overall survival (OS)." (PMID 33240622, 2020). "Our collaborative study with Israel Vlodavsky was the first to show that systemic administration of CXCL10 (CXCL10-Ig) limits cancer in immunocompetent mice." (PMID 32547545, 2020). "A part from chemotaxis, CXCL10 have been reported to promote cancer invasion and to increase invasive properties of RA FLS in vitro in a CXCR3-dependent autocrine fashion." (PMID 31275320, 2019).
cancer (continued). "Most members of the chemokine family, including CXCL1, CXCL2, CXCL5, CXCL9, CXCL10 and CXCL13, where they are secreted by cancer or stromal cells, such as cancer-associated fibroblasts (CAFs) and dendritic cells (DCs)." (PMID 30925930, 2019). "The emerging role of CXCL10 in the pathogenesis of cancer has also included the inflammation-driven cancer, PDAC." (PMID 31415645, 2019). "G-CSF, IL-1b, and CXCL10 are released from the metastasis-derived myeloid cells and all also trigger the NFκB pathway, which plays an important role in the cancer cell response to inflammation." (PMID 31064120, 2019). "We observed a high correlation between CD8+ T cell fractions and the expression of CXCL9 chemokine and chemokine receptor CXCR3 and, for some cancer types, with CXCL10 expression." (PMID 31126321, 2019). "M1 macrophages produce CXCL9 and CXCL10 and exert an anti-tumoral activity, while M2 macrophages sustain cancer growth." (PMID 30319638, 2018). "Inflammation promoted a switch on the CXCR3 ligand profile in normal and cancer epithelial cells, where CXCL10 became the predominant chemokine." (PMID 29416784, 2018). "In this study, we detected changes in the expression of CXCL10 in cancer which was significantly higher than that of normal tissues." (PMID 28176846, 2017). "Lastly, a causative role of chemokine expression was evaluated with an orthotopic mouse model, based on isogenic rectal CT26 cancer cells, engineered to express CXCL10." (PMID 29163806, 2017). "This is also accompanied by increased expression of CXCL12, CXCL10, as well as markers of cancer progression, including CD44, ZEB1 and vimentin." (PMID 28445977, 2017). "Results showed that the rate of cancer cells was slower after transfection, while the rate of siRNA CXCL10 in normal cells was significantly increased (P < 0.05)." (PMID 28176846, 2017). "Further cell experiment indicated that CXCL10 expression obviously declined in cancer cells after its siRNA transfection, which inhibited the cancer cell proliferation and in turn promoted normal cell growth." (PMID 28176846, 2017). "Studies have also found significantly higher CXCL10 protein levels in cancer tissue than in normal paired tissue." (PMID 27034164, 2016). "The availability of clinical grade TLR3 agonists, recombinant type I IFNs, and pre-clinical recombinant CXCL10 provide promising avenues for targeted cancer therapies." (PMID 26486085, 2015). "Anthracycline treated cancer cells also upregulate a TLR3/type I IFN/chemokine (C–X–C motif) ligand 10 (CXCL10) signaling cascade that results in protection from tumor growth." (PMID 26486085, 2015). "Other studies have also reported that the CXCL10 expression is increased in MSCs upon release by cancer cells of Hypoxia-Inducible Factors." (PMID 26362269, 2015). "CXCL10 facilitates trafficking of CXCR3-expressing cancer cells to bone, and promotes osteolytic bone metastasis, implying host involvement." (PMID 26485767, 2015). "In human macrophages, microglia, and epithelial and cancer cells, CXCL-10 expression has been demonstrated to be mediated through MAPK (ERK1/2, JNK, and p38) and STAT1 signaling pathway." (PMID 24696007, 2014). "In this study, we demonstrated that lysates from cancer tissue exhibited significantly higher levels of CXCL10 protein compared to those in paired normal tissues." (PMID 24748971, 2014). "In cancer researches, expression of CXCL10 is mediated through the Raf, PI3K, p38/MAPK, JNK/MAPK, and NF-κB signaling cascades." (PMID 24696007, 2014). "Using Luminex technology for protein analyses, we observed a significantly higher CXCL10 protein level in cancer tissue compared to that in paired normal tissue." (PMID 24748971, 2014). "For the sake of simplicity, in the following sections of the manuscript the four chemokines (CCL2, CCL5, CXCL8, CXCL10) will be referred together as “cancer-related chemokine cluster”." (PMID 24213226, 2012).